INS (insulin)
Diseases named in the same sentence as INS in open-access papers (continued):
Sharing a sentence is not in itself a finding about the gene and the disease.
Insulin resistance (continued). "Further, psychiatric patients treated with probiotics exhibited improved levels of HDL cholesterol, VLDL, triglycerides, insulin resistance, insulin, malondialdehyde, and C-reactive protein." (PMID 35685534, 2022). "Insulin resistance impairs glucose release, leading to a compensatory increase in β-cell insulin secretion that, in turn, leads to a hyperinsulinemia state within the whole body." (PMID 35454311, 2022). "Normal pregnancy is typically a state of insulin resistance because of a surge of placental anti-insulin hormones." (PMID 35432202, 2022). "Indirect methods of measuring insulin resistance are typically based on insulin and/or glucose levels, such as the homeostasis model assessment insulin resistance (HOMA-IR)." (PMID 36079745, 2022). "Type-2 diabetes (T2D) is a complex disorder characterised by hyperglycaemia, insulin resistance (IR) and chronic inflammation of insulin target tissues." (PMID 35677049, 2022). "The development of neuronal insulin resistance by insulin administration is supported by studies reporting reduced downstream insulin signaling in vivo in the PNS of insulin-resistant ob/ob mice in response to either IT or IP) injections of insulin." (PMID 36615728, 2022). "This study showed decreased fasting blood glucose, HbA1c, insulin, and insulin resistance, with a concomitant increase in serum HDL-cholesterol levels." (PMID 35208257, 2022). "Imbalances in insulin-signaling components are evident in diabetes and insulin resistance and can lead to impaired glucose utilization and hyperglycemia." (PMID 36611803, 2022). "Insulin resistance was assessed using fasting serum insulin levels and the Homeostatic Model Assessment of Insulin Resistance (HOMA-IR) index." (PMID 36051734, 2022). "To access insulin resistance and secretion using fasting glucose and insulin concentration, we evaluated HOMA-IR and HOMA-β indexes." (PMID 35409202, 2022). "Insulin resistance decreases the ability of various organs, for example, the liver, skeletal muscle, or adipose tissue—to respond to insulin." (PMID 35453758, 2022). "In order to fully characterize the action between insulin and S597 in IR signaling, we created a cell-based model of severe insulin resistance." (PMID 36151101, 2022). "Second, high selenium upregulates protein tyrosine phosphatase 1B (PTP1B), a key enzyme in triggering fatty acid synthesis and in reverse regulation of insulin signaling, eventually inducing lipid disorders and insulin resistance." (PMID 35711534, 2022). "Unfortunately, nearly 50% of middle-aged adults in the U.S. have insulin resistance, a condition that involves insulin receptor insensitivity and compensatory increase in insulin secretion." (PMID 35458181, 2022). "Mothers consuming low calorie diets rich in refined carbohydrates develop elevated insulin levels, insulin resistance, obesity and metabolic syndrome over decades." (PMID 35252289, 2022). "Skeletal muscle insulin resistance is mainly characterized by impaired insulin-dependent glucose uptake." (PMID 35782940, 2022). "The homeostatic model assessment (HOMA), based on fasting glucose and fasting insulin levels, was employed to index insulin resistance." (PMID 35565811, 2022). "Female patrilineal F2 mice showed significantly higher serum insulin levels and homeostatic model assessment–insulin resistance (HOMA-IR) in the H-O2-HFD + BPAmf group than in the LFD group." (PMID 35281091, 2022). "A growing number of subjects develop severe insulin resistance necessitating large doses of insulin." (PMID 36013252, 2022). "In particular, PWS children show lower insulin and C-peptide levels, lower insulin resistance, as well as higher adiponectin and HDL cholesterol levels." (PMID 35774143, 2022). "Previous studies suggest that BCAA leads to insulin resistance by interfering with insulin signaling pathways." (PMID 36361016, 2022).
Insulin resistance (continued). "Several studies in animal models have suggested an important role of MR in the development of obesity-related insulin resistance and an insulin-sensitizing effect of MRAs." (PMID 36432422, 2022). "Insulin resistance (IR), a state of tissue resistance to insulin due to its impaired function, is a common coexisting condition." (PMID 35742405, 2022). "For example, IL-6 directly inhibits insulin sensitivity and upregulates the release of hormones that contribute to insulin resistance via induction by insulin receptor's signal transduction in hepatocytes." (PMID 35647197, 2022). "Aberrant insulin signaling and the development of insulin resistance affect the expression of insulin degrading enzyme and consequently Aβ degradation." (PMID 36012331, 2022). "TG(18:1_18:2_18:2) specifically has been identified as being negatively correlated with homeostatic maintenance for insulin resistance in a variety of lipoproteins and deceases in abundance correspond to increases in brain insulin resistance." (PMID 35208224, 2022). "A body of literature proposes that low insulin clearance in BA populations is secondary to insulin resistance." (PMID 34661756, 2022). "The expression “insulin resistance” as commonly considered in the clinical setting refers to the inability of insulin to maintain normal glucose homeostasis." (PMID 36289636, 2022). "The present study highlights the insulin-sensitizing role of T. crispa on insulin resistance pathogenesis by network pharmacology and molecular docking study." (PMID 35737707, 2022). "The major pathophysiological events that contribute to diabetes include impaired insulin function, oxidative stress, inflammation, impaired glucose tolerance (insulin resistance) and which eventually results in altered glucose homeostasis and end up in T2DM." (PMID 36014419, 2022). "Insulin resistance per se has also been theorised as a potential mechanism for delayed SA, given the integral role of insulin in milk production." (PMID 35405936, 2022). "This is indicative of a vicious cycle: insulin-induced weight gain and subsequent weight-induced insulin resistance require higher doses of insulin to achieve glycemic targets." (PMID 35745754, 2022). "Insulin resistance (IR) in insulin-sensitive tissues has been considered as a critical determinant of development and progression of NAFLD." (PMID 36457551, 2022). "Insulin resistance is regarded as the damage to insulin signal transduction occurring when normal hormone concentrations in the blood are insufficient to regulate metabolic pathways." (PMID 36714657, 2022). "Decreased insulin sensitivity or insulin resistance is a hepatic component of metabolic syndrome, leading to increased blood glucose, triglyceride, and cholesterol levels." (PMID 36386217, 2022). "Certainly, in more severe cases of insulin resistance reduced phosphorylation of the insulin signaling pathway components are observed and so increased levels of insulin are required for activation and downstream metabolic effects." (PMID 36038539, 2022). "Central system insulin resistance leads to the reduction of neurocognitive function in T2DM patients by affecting the function of insulin in the brain." (PMID 36699515, 2022). "In an animal study, C57B/6 mice exposed to benzene showed insulin resistance by inhibiting insulin-stimulated Akt phosphorylation and enhanced nuclear kappa phosphorylation." (PMID 36242012, 2022). "Inadequate response of muscle cells, hepatic cells, and adipocytes to insulin gives rise to insulin resistance." (PMID 36004027, 2022). "The disruption of hypothalamic insulin and leptin pathways in POMC neurons, driven by insulin and leptin receptors deletion in these neurons, leads to a state of systemic insulin resistance and deterioration of glucose homeostasis." (PMID 35406040, 2022).
Insulin resistance (continued). "When IL-6 is produced by the skeletal muscle it increases insulin sensitivity whereas its (IL-6) release from adipocytes and macrophages leads to an increase in insulin resistance." (PMID 36778598, 2022). "To assess the potential to induce insulin resistance, we tested the secreted proteins in rat primary myocytes and followed their ability to affect insulin-mediated glucose uptake." (PMID 36513656, 2022). "In the muscle tissue, insulin resistance, defined as a complex pathological state in which insulin-dependent cells fail to respond to insulin, is considered to be a primary defect of T2D, occurring before β-cell failure." (PMID 39872972, 2022). "Insulin resistance in overweight has recently been shown to reduce the inhibitory function of insulin in the human brain." (PMID 36170006, 2022). "Insulin levels rise chronically in obesity, and type 2 diabetes, which is characterised by insulin resistance and thus high circulating levels of insulin." (PMID 36038791, 2022). "Insignificant differences in fasting blood glucose, insulin, homeostatic model assessment of insulin resistance, quantitative insulin sensitivity check index, hs-CRP and homocysteine levels were also observed after DRB intervention." (PMID 36045411, 2022). "Insulin resistance at peripheral tissues results in decreased insulin-stimulated glucose uptake in skeletal muscle and white adipocytes, and impaired suppression of liver glucose production." (PMID 36093112, 2022). "There was a positive correlation of insulin resistance with the serum insulin, ferritin levels, cholesterol, LDL and triglyceride level and a negative correlation with the serum HDL level." (PMID 35893594, 2022). "Insulin resistance (IR) refers to the decreased sensitivity of surrounding target tissues to insulin, such as the liver, muscle, and adipose tissue." (PMID 36249806, 2022). "Systemic insulin resistance is characterized by reduced insulin metabolic signaling and glucose intolerance." (PMID 36012219, 2022). "Future studies should examine the relationship between these microbiota taxa and host physiology factors as glucose and insulin levels, or the Homeostatic Model Assessment for Insulin Resistance (HOMA index), as potential early predictive markers of T2DM." (PMID 35205333, 2022). "In insulin resistance, defects in this signal transduction reduce insulin-stimulated glucose uptake." (PMID 36439272, 2022). "In the palmitate condition, we identified 689 phosphoproteins from the insulin treatment (Ins) and insulin resistance–insulin treatment (IR + Ins) groups." (PMID 35055191, 2022). "Body mass index (BMI), serum fasting glucose, insulin, and lipid profiles including triglycerides (TG) and high-density lipoprotein were measured, and the homeostatic model assessment for insulin resistance (HOMA-IR) index was evaluated." (PMID 35215377, 2022). "Other arachidonic acid-derived lipid mediators such as PGE2 produced in Kupffer cells and infiltrating macrophages in insulin-resistant livers plays an ambiguous role in the development of insulin resistance." (PMID 35955975, 2022). "We previously showed that in vitro treatment of neurons with insulin or palmitate for 24 h produces insulin resistance, providing a cell culture model of prediabetes, with the expected changes in cellular signaling pathways." (PMID 36248795, 2022). "Inadequate insulin production or insulin resistance hinders proper glucose homeostasis, resulting in hyperglycemia." (PMID 36297746, 2022). "The common etiology of MetS is insulin resistance developed when insulin action is attenuated due to aging, obesity, sedentary lifestyles, smoking, and sleep apnea." (PMID 35624721, 2022). "Because HOMA-IR is the index which more consistently predicts insulin resistance than others, we further calculated HOMA-IR based on fasting plasma glucose and insulin levels." (PMID 35629946, 2022).
Insulin resistance (continued). "Increased expression of CUG-BP, a regulator of pre-mRNA splicing, caused a switch from IR-B to IR-A in skeletal muscle, resulting in reduced insulin signaling activation and contributing to insulin resistance." (PMID 36589630, 2022). "As the main pathogenesis of T2DM, insulin resistance runs through the whole disease process, induced by impaired insulin signaling transduction and quantified by a steady-state model evaluation of the HOMA-IR score." (PMID 35153796, 2022). "Type 2 diabetes is characterized by insulin resistance, impaired hepatic glucose homeostasis and dysregulated insulin secretion." (PMID 36589440, 2022). "PKC-θ knockout mice are protected against fat-induced insulin signaling defects and systemic insulin resistance." (PMID 36230963, 2022). "One additional barrier is known as “psychological insulin resistance,” where patients are hesitant to initiate and or adhere to insulin therapy." (PMID 35943787, 2022). "Twelve-week administration of C. lacerata in T2DM patients resulted in significant improvement in insulin resistance, especially in those with lower insulin sensitivity." (PMID 35242882, 2022). "Participants in TG-WC group had the highest BMI, WC, blood pressure (BP), insulin, Homeostatic Model Assessment of Insulin Resistance (HOMA-IR), glycosylated hemoglobin (HbA1c), low-density lipoprotein cholesterol (LDL), and fatty liver." (PMID 35165286, 2022). "Insulin can mediate antilipolysis, but adipose tissue insulin resistance can reduce this effect, lowering lipoprotein lipase activity and further triggering hyperlipidemia." (PMID 35340412, 2022). "High insulin demand is imposed on β-cell in the presence of insulin resistance, which stimulates the synthesis of insulin and is likely to promote the misfolding of insulin." (PMID 35929791, 2022). "In diabetic rats, Khan and Jena observed lower HBA1c and plasma glucose with unchanged plasma insulin when given butyrate, thus showing that butyrate decreases insulin resistance." (PMID 35054972, 2022). "Insulin elevation and insulin resistance positive correlation with clozapine levels as well as norclozapine/clozapine ratios were also reported in a later study." (PMID 35890117, 2022). "Insulin resistance is typically defined as decreased sensitivity to the metabolic activity of insulin and is observed in patients with type 2 diabetes mellitus and obesity." (PMID 36099304, 2022). "Once again, ROS upregulates peroxynitrite production and prevents the dilatation of the arterial wall, while insulin signaling in the endothelial cells is impaired, further aggravating insulin resistance and inflammation." (PMID 36289641, 2022). "Insulin resistance is a condition whereby insulin-induced glucose uptake is impaired in the insulin-sensitive tissue." (PMID 35982478, 2022). "PPARγ activators are used as insulin sensitizers in order to improve insulin resistance in diabetic patients." (PMID 36501129, 2022). "Type 2 diabetes results from long periods of increased insulin resistance with high circulating insulin levels that lead to eventual islet beta cell failure." (PMID 35745248, 2022). "T2DM is characterized by insulin resistance (impaired responses to insulin) and β-cell dysfunction (inadequate insulin synthesis)." (PMID 36232419, 2022). "DM is a progressive metabolic disorder characterized by chronic persistent hyperglycemia, insulin resistance and impaired insulin synthesis with elevated hepatic glucose outputs." (PMID 36014565, 2022). "The induction of autophagy suppresses obesity-driven insulin resistance due to adipocyte dysfunction and defaulted insulin signaling pathways in adipose tissue." (PMID 36523600, 2022). "Greater reductions in fasting insulin concentration and insulin resistance (HOMA-IR) were reported following 5:2 IER compared with CER in two similar studies, however, 2-day energy restriction was on consecutive days and participants had overweight or obesity." (PMID 34040199, 2022).
Insulin resistance (continued). "Insulin resistance and insulin signaling pathway were the most major pathways affected by gut microbiome changes in PCOS." (PMID 36338055, 2022). "As broadly defined, insulin resistance refers to a reduced insulin-mediated glucose uptake eliciting compensatory hyperinsulinemia that is needed to maintain glucose levels within normal limits." (PMID 36289636, 2022). "Impaired insulin signaling, commonly known as insulin resistance, plays an important role in the development of DCM." (PMID 36405687, 2022). "As well as relatively ‘clean’ defects in insulin action or adipose tissue development/function, a wide range of rare disorders have been described where severe insulin resistance is part of a more complex syndrome." (PMID 35618782, 2022). "During the second trimester (13–28 weeks of gestation) of pregnancy insulin resistance increases and glucose levels rise in women unable to produce enough insulin to adopt this resistance." (PMID 35090536, 2022). "HFD-induced brain insulin resistance decreased insulin clearance and insulin-degrading enzyme (IDE) levels significantly after geraniol supplementation." (PMID 36304965, 2022). "In both groups of subjects, anthropometric indices, lipid profile, glucose metabolic parameters, HbA1c, the homeostasis model assessment estimate of HOMA-insulin resistance (IR), and the insulin sensitivity index (ISI) were evaluated." (PMID 35432528, 2022). "Subsequent OGTT results also supported this notion, with high doses of SA significantly improving glucose tolerance in T2DM mice, lowering blood insulin levels, ameliorating insulin resistance, and promoting glucose metabolism." (PMID 36618687, 2022). "Fasting serum insulin levels increased significantly in the DM group, representing insulin resistance." (PMID 36276816, 2022). "At the metabolic level, insulin resistance in obesity and type 2 diabetes is characterized by reduced insulin-stimulated glucose uptake and glucose storage in skeletal muscle." (PMID 36387850, 2022). "The importance of insulin resistance in disease pathogenesis lagged behind insulin response, as resistance was more difficult to measure than secretion." (PMID 35163746, 2022). "Another study positively correlated serum RBP4 levels with insulin resistance and additionally showed that improving insulin sensitivity through exercise lowers RBP4 levels." (PMID 35334893, 2022). "Most studies have demonstrated an inverse relationship between birth weight and plasma glucose and insulin levels, type 2 diabetes mellitus and insulin resistance." (PMID 36005598, 2022). "The released inflammatory mediators directly inhibit the action of insulin and are involved in the development and progression of insulin resistance." (PMID 35079646, 2022). "Niacin reduces lipolysis and stimulates an increase in glucose levels, which results in stimulation of insulin secretion and reduced insulin resistance." (PMID 35739861, 2022). "Increased IL-6 release from adipose tissue contributes to the development of insulin resistance either by reducing adiponectin secretion, as demonstrated by our findings, or by influencing the insulin signal transduction pathway in hepatocytes." (PMID 36364860, 2022). "Calorie restriction has been shown to improve insulin resistance, lower blood lipids, fasting insulin and reduce inflammation." (PMID 36432420, 2022). "Presumably, pancreatic β cells and tissues that clear insulin sense the need to secrete more and clear less insulin to prevent hyperglycemia when there is insulin resistance, and this compensatory mechanism is impaired in people with T2D." (PMID 35054781, 2022). "These three results indicated that MLF can improve the insulin resistance, reduce the level of blood glucose and insulin, and improve glucose metabolism disorder." (PMID 35845591, 2022). "In an insulin-resistant state, Na+/K+-ATPase activity is decreased, and insulin resistance induces hyperinsulinaemia." (PMID 36499723, 2022).